IRF1 (interferon regulatory factor 1)
Diseases named in the same sentence as IRF1 in open-access papers (continued):
Sharing a sentence is not in itself a finding about the gene and the disease.
gastric cancer (continued). "Thus, IRF1 up-regulation may be responsible for the increase in DHRS3 that ATRA triggers in gastric-cancer cells." (PMID 37951921, 2023). "In the progression of gastric cancer (GC), one study shows that SNP rs56288038 (C/G) in IRF-1 3′UTR promotes GC development by enhancing the regulatory role of miR-502-5p in IRF-1 expression." (PMID 32821248, 2020). "Moreover, IFN-γ induced the IRF-1-mediated downregulation of MIR17HG in gastric cancer cells." (PMID 31186404, 2019). "In particular, the IRF1 gene is likely to play a key role in the IFN-dependent and immunological responses activated by ATRA in gastric-cancer." (PMID 37951921, 2023). "The interaction of the transcription factors RELA, IRF1, ESR1, AR, POU5F1, TRIM28, and GATA1 with LOC441461 affected the degree of the malignancy of gastric cancer by modulating gene transcription." (PMID 35267457, 2022). "Overall, we suggest that LOC441461 modulates gene transcription, inducing the malignancy of gastric cancer by interacting with RELA, IRF1, ESR1, AR, POU5F1, TRIM28, and GATA1." (PMID 35267457, 2022). "A final and significant outcome of our study is the identification of a restricted number of genes which are up-regulated (IRF1, CTSS, PSMB10, CYP26B1, DHRS3 and TINAGL1) and down-regulated (AHNAK2) by ATRA in all the retinoid-sensitive gastric-cancer cell-lines considered." (PMID 37951921, 2023). "In addition, both IRF1 and IFI6 are positively correlated with the drug-specific chemical sensitivity of gastric cancer." (PMID 34082779, 2021). "Interestingly, IRF-1 could reverse the multiple drug resistance of gastric cancer by decreasing the expression of P-glycoprotein, and high expression of IRF-1 contributes to 5-fluorouracil chemosensitivity in gastric cancer cells." (PMID 35092496, 2022).
ovarian carcinoma (22 papers, 1999 to 2025). A malignant neoplasm originating from the surface ovarian epithelium. "IRF1 activity in ovarian cancer cells was also associated with resistance to paclitaxel, another chemotherapeutic agent." (PMID 38396830, 2024). "Some studies show the association of IRF1 overexpression with increased overall survival of ovarian carcinoma patients." (PMID 35810383, 2022). "Interestingly, we have identified IRF-1 previously as a gene associated with the response of ovarian cancer cells to platinum." (PMID 27027433, 2016). "Cisplatin exposure was found to increase IRF1 expression in ovarian cancer cells, resulting in p21-dependent cell cycle arrest and a further paradoxical decrease in sensitivity to cisplatin." (PMID 38396830, 2024). "It is controversial that IRF1 expression is upregulated by cisplatin, but limits drug effectiveness in ovarian cancer cells." (PMID 32326356, 2020). "Hyper-SUMOylation of IRF1 has been detected in ovarian cancers, and is known to disrupt IRF1 transcriptional activity." (PMID 30854564, 2019). "We have already shown also that IRF-1 expression is functionally correlated to platinum resistance of ovarian cancer cells as it is 2-fold increased after cisplatin treatment and limits cell response to this drug." (PMID 27027433, 2016). "It has been observed that the degree of T cell infiltration in ovarian cancer correlated with the expression of the interferon regulatory factor IRF1, the major transcriptional activator of genes induced by alpha, beta and gamma interferons." (PMID 27871313, 2016). "Positive staining of IRF1 was predominantly observed in ovarian cancer cells (cell lines and tumors) with lesser but detectable expression observed in tumor infiltrating lymphocytes." (PMID 27871313, 2016). "The network based approach identified two 7-gene functional interaction modules (31: DCLRE1A, EXO1, KIAA0101, KIN, PCNA, POLD3, POLD2; 35: DKK3, FABP3, IRF1, AIM2, GBP1, GBP2, IRF2) that are associated with prognosis of ovarian cancer patients." (PMID 27806724, 2016). "Previous studies have revealed that IRF1 may contribute to the risk of PCOS through developmental mechanisms, and it exhibits high expression levels in ovarian cancer." (PMID 39735641, 2024). "Furthermore, IRF1 directly mediates the interferon-γ (IFN-γ)-induced apoptosis via the activation of caspase-1 gene expression in IFN-γ-sensitive ovarian cancer cells." (PMID 27806724, 2016). "A previous study has demonstrated that increased level of IRF1 is associated with both increased progression-free and overall survival of patients with ovarian carcinoma, and IRF1 is an independent predictor of platinum resistance and survival in high-grade serous ovarian carcinoma." (PMID 27806724, 2016). "Thus, continuous interaction with the IFN-γ receptor, together with a sustained induction of p21 and IRF-1, is associated with growth inhibitory and apoptotic effects of IFN-γ in ovarian cancer cells." (PMID 10376977, 1999). "The elevated procaspase 9 and IRF-1 may be triggering apoptosis in human ovarian cancer cell lines." (PMID 37389738, 2023). "However, IRF1 silencing improved Taxol sensitivity in ovarian cancer cells." (PMID 35810383, 2022). "A study found that the expression of IRF1 and STRA6 was markedly upregulated in the ovarian cancer cell line HEY." (PMID 41465326, 2025). "In ovarian cancer cells, the increase in CD274 transcription in response to IFNγ stimulation of cells was confirmed to occur under the control of the JAK1/STAT1/IRF1 signaling pathway." (PMID 38396830, 2024). "Through miRNA, these lncRNAs are connected with PRGs such as IRF1, NOD1, GSDMC, NLRP1, PLCG1, GSDME and GZMB to construct a pyroptosis related ceRNA regulatory network in ovarian cancer." (PMID 37859811, 2023). "Only two of these genes, IRF-1 and CXCR6, were also found to be differentially expressed in our cohort of 49 serous advanced-stage ovarian cancer patients (P=0.018578 resp." (PMID 20664601, 2010).
ovarian carcinoma (continued). "Thus, we discovered many unproven pyroptosis related regulatory axes in ovarian cancer, such as KRT7-AS—has-miR-205—GSDMC, LINC01094—has-miR-330-3p—IRF1, ZNF32-AS2—has-miR-214—GSDME, and MYCNOS—has-miR-150—NLRP1." (PMID 37859811, 2023). "Unlike outcomes in the ovarian cancer study, most of the regulatory relationships here are linear, only IRF1 and NFE2 in Monocyte cell line show nonlinear regulations." (PMID 33256599, 2020). "However, in a recent study of ovarian cancer, IRF-1 was identified to be up-regulated in ovarian cancer samples compared with healthy ovarian tissue although strong expression of IRF-1 predicted improved disease-free survival and overall survival." (PMID 27806724, 2016). "However, this study does not defy the tumor-suppressive role of IRF1 because IRF1 overexpression still inhibits the transformed phenotypes of ovarian cancer cells." (PMID 32326356, 2020).
colon carcinoma (21 papers, 2016 to 2026). "Nonetheless, Irf1-deficient animals exhibited an atypical vulnerability to colitis-associated colon cancers." (PMID 40422233, 2025). "Literature reports that SPI1 interacts with IRF1 or TIMP1 to regulate the sensitivity of colon cancer to ferroptosis." (PMID 41372608, 2025). "Conversely, protective genes such as PAEP, TAP2, CXCL10, and IRF1 were notably down-regulated in colon cancer cells." (PMID 40959081, 2025). "For the identification of IRF1 stability regulators, we characterized IRF1 degradation properties in the human RKO colon carcinoma cell line, as it is highly amenable for genetic screening." (PMID 37622993, 2023). "First, we examined the expression of IRFs and found that, RNA expression of IRF1 and 7 was increased in both IFNγ-stimulated murine colon cancer cells." (PMID 37380972, 2023). "The interferon-stimulated response element (ISRE) in the exon 1 of PIGR gene in HT-29 human colon carcinoma cells binds IRF-1 following the stimulation of IFNγ to enhance the transcription of pIgR." (PMID 35493520, 2022). "Since, PD-L1, IRF1, IFN-γ and IFN-γ associated immune gene were important features of MSI status, we then investigated the roles of those genes in colon cancer progress." (PMID 31221124, 2019). "In the MSI subtype colon cancer patients’ datasets, we showed that IRF1 was highly up regulated in MSI patients." (PMID 31221124, 2019). "Notably, the related HATs CBP and P300, which interact directly with IRF1 in human glioblastoma and colon cancer cell lines, are essential for HSC and embryonic stem cell self-renewal and differentiation." (PMID 37889967, 2023). "Here, evidences from 7 expression datasets showing that MSI subtype colon cancer patients maintain immune activated statues, and PD-L1, IFN-γ, IFN-γ associated immune gene signature and transcription factor IRF1 are highly expressed in the MSI subtype colon cancer patients." (PMID 31221124, 2019). "The investigation of IRF1’s role in carcinogenesis through PANoptosis revealed that IRF1 substantially decreases CRC incidence in mice, and the induction of PANoptosis successfully inhibits AOM/DSS-induced colon cancer." (PMID 40422233, 2025). "IRF1 and IRF8 are member of the IFN regulatory factor family; both of them were proven to be suppressor of colon cancer." (PMID 32812032, 2020). "Previously, it was shown that interferon regulatory factor 1 (IRF1) regulated IFN-γ-induced PD-L1 expression in lung, liver and colon cancer cells." (PMID 30185888, 2018). "However, although all the tested colon cancer cell lines were responsive to IFN-γ, as revealed by induction of ISGs14, 15 such as STAT-1, STAT-3, interferon responsive factor (IRF-1), and BCLXL, unexpectedly MMP-1 mRNA levels were reduced following IFN-γ treatment (18 h)." (PMID 28819304, 2017).
colitis (18 papers, 2015 to 2025). Inflammation of the colon. "In the human gut, IRF-1 upregulation has been associated with chronic intestinal inflammation, while studies of Irf1–/– mice in a mouse model of chemically induced colitis suggested protective roles during intestinal inflammation." (PMID 36175404, 2022). "So, while in our experimental model of CA-CRC, the milder DSS alone treatment did not reveal a differential colitic response in mutant mice, under prolonged conditions, Irf1 mutant mice can show signs of increased susceptibility to DSS-induced colitis." (PMID 31827213, 2019). "Interferon regulatory factor 1 (IRF1) has also been identified as an upstream regulator of PANoptosis that prevents tumorigenesis in a spontaneous mouse model of CRC by inducing cell death during colitis-associated tumorigenesis." (PMID 38553639, 2024). "In addition, as an activator of PANoptosis, interferon regulatory factor 1 can induce inflammatory cell death during colitis-associated tumorigenesis." (PMID 37666920, 2023). "The Carinh/Irf1 relationship is sustained by microbial factors, and when colitis appears, Carinh/Irf1 regulates the induction of the anti-inflammatory factor IL-18BP." (PMID 39201494, 2024). "DCs exhibited the lowest M1 and M2 scores, while mono- and inflammatory macrophages displayed higher M1 scores, indicating the dominance of pro-inflammatory macrophages during colitis (related to Il1b, Irf1, Cd14, Fcgr3 expression level)." (PMID 38674054, 2024). "Our results mechanistically highlight the fine regulatory relationship that exists between the lncRNA Carinh and its neighboring gene Irf1 to protect the host against colitis." (PMID 37055591, 2023). "We further investigated the mechanism by which myeloid Carinh promotes Irf1 transcription to protect against DSS-induced colitis." (PMID 37055591, 2023). "When colitis is triggered, Carinh/IRF1 regulates the induction of the anti-inflammatory factor IL-18BP to prevent further inflammation and colitis exacerbation." (PMID 37055591, 2023). "Furthermore, both the mRNA and protein expression of Irf1 and Casp1 were significantly upregulated in the colitis rats compared to the controls." (PMID 40018047, 2025). "Additionally, the colitis rat model validated the upregulation of Irf1 and Casp1 at both mRNA and protein levels." (PMID 40018047, 2025). "For example, Karki study showed that knockdown of interferon regulatory factor 1 could significantly inhibit the activation of GSDMD (pyroptosis), CASP3/7 (apoptosis) and MLKL (necroptosis), thereby promoting cell death in colitis-associated CRC." (PMID 39331898, 2024). "In fact, Carinh and the gene Irf1 protect the host against colitis." (PMID 39201494, 2024). "Thus, we speculated whether Carinh protects against DSS-induced colitis through the regulation of IRF1." (PMID 37055591, 2023). "The IRF1 and IRF2 binding sites were over-represented in the up-regulated genes in pediatric IBD and experimental colitis." (PMID 26085826, 2015). "The effect of Irf1 inactivation on response to intestinal inflammation and injury was then tested in mouse models of colitis induced by chronic exposure to DSS without AOM treatment." (PMID 31827213, 2019). "Thus, IRF1 and IRF2 have the potential to be selective and potentially effective targets for the treatment of both experimental colitis and pediatric IBD." (PMID 26085826, 2015).
asthma (17 papers, 2013 to 2026). "A genome‐wide study, the IRF1 locus is a strong candidate region for specific asthma susceptibility." (PMID 41573111, 2026). "Five druggable genes significantly associated with asthma were identified in whole blood (IRF1, OXER1, PSMA4, UNC13D, and HLA‐DRB1) and one in lung tissue (CD226)." (PMID 41573111, 2026). "It is also notable in this context that IRF1 gene variants have been linked to childhood asthma risk and dysregulated proinflammatory responses." (PMID 35990635, 2022). "A cohort study has suggested that IRF1 is associated with the risk of asthma." (PMID 40420582, 2025). "Furthermore, severe, or uncontrolled asthma is associated with viral exacerbations and IRF1 is implicated in these steroid-resistant responses to viral infection." (PMID 41359631, 2025). "Many previous studies have shown that the IRF1 gene has an inflammatory effect, leading to acute asthma attacks." (PMID 41573111, 2026). "Based on the PhenomeXcan platform, we observed that IRF1 was significantly associated with ARDS-related traits in the UK Biobank (q-FDR ≤ 0.05), including eosinophil, platelet, white blood cell, monocyte, asthma, and lung function." (PMID 40420582, 2025). "In turn, ANCA-negative EGPA has a mucosal barrier origin and is associated with variants of the glycoprotein A33 (GPA33) and IL-5/interferon regulatory factor 1 (IRF1) (genotype sharing with asthma)." (PMID 37215720, 2023). "MiR-342-5p is coupled to the antiviral interferon (IFN) response via IFN regulatory factor 1 (IRF1) and plays roles in both asthma and respiratory infections." (PMID 37076662, 2023). "The present project confirms that the loss of GLCCI1 expression leads to GC insensitivity through downregulating the GR-GRIP1 pathway, which is associated with the increased interaction between IRF1 and GRIP1 and between IRF3 and GRIP1 in asthma." (PMID 34504850, 2021). "The association of this locus to inflammatory bowel disease, the known link between the IRF1 pathway and IBD, and the link between IRF1 variants and eczema and asthma suggest that genetic IRF1 dysregulation affects disease risk." (PMID 34314424, 2021). "This project determines the underlying mechanism that GLCCI1 deficiency attenuates GC sensitivity in dexamethasone (Dex)-treated Ovalbumin (OVA)-induced asthma mice and epithelial cells through upregulating binding of IRF1:GRIP1 and IRF3:GRIP1." (PMID 34504850, 2021). "IRF1 (PPH4/PPH3 + PPH4 = 0.975), OXER1(PPH4/PPH3 + PPH4 = 0.967), PSMA4(PPH4/PPH3 + PPH4 = 0.972), UNC13D (PPH4/PPH3 + PPH4 = 0.989) and HLA‐DRB1(PPH4/PPH3 + PPH4 = 0.948) expression had significant colocalization associations with asthma." (PMID 41573111, 2026). "Therefore, it can be used to assist in the treatment of acute exacerbations of asthma by controlling IRF1 levels." (PMID 41573111, 2026). "The IRF1‐HLA‐DRB1 axis represents a key immunoregulatory pathway in asthma pathogenesis." (PMID 41573111, 2026). "IRF1 could therefore be explored as a therapeutic target in glucocorticoid resistant diseases such as severe asthma, or high levels of IRF1 expression may act as a biomarker of glucocorticoid insensitive disease." (PMID 41359631, 2025). "Increased IRF1 and IRF3 expression might take part in GLCCI1 deficiency-induced GC insensitivity in asthma." (PMID 34504850, 2021). "However, further work must be carried out to fully understand the impact of IRF1 signalling on Th9 cells during asthma exacerbations." (PMID 28497800, 2017). "The knowledge of this IRF1-mediated transition of Th9 differentiation could prove useful for further unravelling Th9- and IFN-γ-associated immune responses during asthma as well as antitumour immunity." (PMID 28497800, 2017). "Indeed retinoic acid not only has been shown to play a role in cell death in myeloid cells by activating Interferon Regulatory Factor 1 and, implicitly, increasing interferon responses but also has an exacerbating effect on asthma in mouse models." (PMID 23882263, 2013).
asthma (continued). "IRF1-dependent gene expression may therefore show insensitivity to glucocorticoid and could contribute to glucocorticoid-resistance in diseases that include severe asthma." (PMID 41359631, 2025). "This line of interrogation is of particular importance since IRF1 is known to play roles in the transcriptional regulation of inflammatory genes that include the chemokine, CXCL10, which may be induced by IL-1β or TNFα and is implicated in severe asthma." (PMID 41359631, 2025). "To induce asthma pathophysiology in the mouse model, we performed adoptive transfer experiments of OVA-transgenic IFN-γ-treated WT and Irf1−/− Th9 cells into Rag2−/− mice and subsequently challenged the mice with nebulized OVA." (PMID 28497800, 2017).